HJURP (Holliday junction recognition protein)
Diseases named in the same sentence as HJURP in open-access papers (continued):
Sharing a sentence is not in itself a finding about the gene and the disease.
tumor (continued). "Epigenetic modifications of abnormal HJURP occur at the very early stages of tumor development, and HJURP has functional effects on different types of tumors through different mechanisms of action, which deserve further investigation." (PMID 36460821, 2022). "HJURP was ectopically upregulated in CCAs compared with the para-tumor tissues based on TCGA and other mRNA-seq databases." (PMID 35965590, 2022). "We validated the differential expression of HJURP in tumor-infiltrating CD8+ T cells, sorted by flow cytometry into populations based on the expression level of PD-1." (PMID 35783358, 2022). "In summary, this is the first study to explore the role of differential HJURP expression and its methylation in various tumor cohorts." (PMID 36460821, 2022). "Then, to further investigate the combined effect between HJURP knockdown and cisplatin treatment on tumor inhibition, in vivo experiment was performed." (PMID 35173547, 2022). "Meanwhile, overexpression of HJURP is also found to regulate tumor cell growth in vivo, while tumor cell invasion in vitro predicts the poor prognosis of the disease." (PMID 36460821, 2022). "We further performed tumor-forming animal experiments in nude mice that showed that tumor volume is significantly reduced after downregulation of HJURP especially when treated with doxorubicin." (PMID 35459269, 2022). "It was found that compared with normal tissues, HJURP expression was significantly higher in most types of tumor tissues and high expression of HJURP was related to poorer prognosis." (PMID 36460821, 2022). "IOBR further suggested a link between HJURP and other tumor signatures such as DDR, mismatch repair, and homologous recombination." (PMID 35783358, 2022). "HJURP was highly expressed in CD8+ T cells, dendritic cells, and hepatocytes, which verified the correlation between HJURP and tumor-infiltrating immune cells." (PMID 35783358, 2022). "In view of the probable role of HJURP in chromosomal stability and tumor progression that we have expounded above, HJURP was further focused on in the present study." (PMID 35173547, 2022). "According to TCGA-BRCA data, the expression of the positive genes of risk score (HJURP, IFI27, RAD51AP1, EZH2, DNMT3B, SLC7A5, DBF4 and USP18) in tumors was higher than that in normal and tumor-adjacent tissues." (PMID 36341435, 2022). "A multivariable Cox regression model was defined using data on HCC patients from the TCGA-LIHC cohort, HJURP expression and other independent prognostic factors, including age, gender, Child-Pugh liver function classification, and tumor stage." (PMID 35783358, 2022). "We found that depletion of HJURP led to decreased tumor size and was more sensitive to doxorubicin, suggesting that HJURP activation is important for TNBC tumor growth and chemotherapy response in vivo." (PMID 35459269, 2022). "Researchers can use our nomograms to predict the clinical prognosis of specific individuals based on the age, gender, pathological tumor stage, and the absolute expression of HJURP (transcripts per kilobase of per million mapped reads)." (PMID 35274047, 2022). "As revealed by the results of previous studies, the hypomethylation of HJURP can promote tumor development by reducing the stalling of G0/G1 in the cell cycle." (PMID 36460821, 2022). "This work aimed to explore the differential expression, tumor treatment and prognosis of HJURP in different types of tumor cohorts." (PMID 36460821, 2022). "Thereafter, the mRNA data and clinical characteristics of 33 tumor types from TCGA database were obtained to investigate the expression and prognostic relationship of HJURP in different tumor types." (PMID 36460821, 2022). "HJURP can participate in various cell proliferation-related pathways and promote the proliferation of tumor cells, such as HCC." (PMID 36460821, 2022).
tumor (continued). "Previous experimental reports have indicated that the hypomethylation of HJURP is highly expressed in tumors, which promotes the progression and migration of tumor cells." (PMID 36460821, 2022). "In PCa, 137 genes were differentially expressed between tumor and normal tissues, which HJURP was most significantly upregulated in PCa (fold change = 6.2, P < 0.05), and its mRNA levels were substantially elevated among the eight tumors." (PMID 34099634, 2021). "Subsequently, cell viability and sphere formation assays were performed to detect the impact of HJURP on tumor proliferation." (PMID 32439850, 2020). "According to current studies, HJURP acts as a tumor promoter in HCC by mediating cell proliferation, migration, and invasion both in vitro and in vivo." (PMID 32439850, 2020). "(A) Protein levels of HJURP in tumor tissue (staining: High; intensity: Moderate; quantity: 75–25%; Location:Cytoplasmic/membran)." (PMID 31139013, 2019). "Subsequently, cell viability and colony formation assays were performed to examine the role of HJURP in tumor proliferation." (PMID 30111352, 2018). "In contrast, the overexpression of HJURP in the SMMC-7721 cells markedly promoted tumor growth in vivo." (PMID 30111352, 2018). "The data revealed that p21 silencing reversed the tumor promoting activity of HJURP indicated by CCK-8 assays, colony formation assays and cell cycle analysis." (PMID 30111352, 2018). "Given that HJURP modulates tumor growth through p21, we depleted p21 expression in HJURP-silenced HCC cells and examined the colony formation and proliferation." (PMID 30111352, 2018). "We thus tested the impact of HJURP depletion in pre-established allograft tumors in mice and revealed a major block of tumor progression in vivo." (PMID 28356341, 2017). "Quantification of the number of foci in the nuclei of tumor cells revealed a twofold decrease in HJURP off tumors." (PMID 28356341, 2017). "Closer inspection of viable areas from tumor sections revealed that more cells were positive for cleaved caspase-3 and γH2A.X in the Hjurp-depleted tumors than in the control tumors, suggesting that loss of HJURP may also lead to genome instability and apoptosis." (PMID 28356341, 2017). "In the present study, we observed significantly higher expression of HJURP protein in HCC tissues compared with paired adjacent non-tumor tissues." (PMID 26863619, 2016). "By IHC, we detected greater expression of HJURP protein in HCC tissues than in paired adjacent non-tumor liver tissues (N = 60, P = 0.0010)." (PMID 26863619, 2016). "A lower expression of HJURP was observed in both tumor and stromal cells and was more evident in the latter, with no significant variation between G1-2 and G3 lesions." (PMID 25243117, 2014). "On the basis of these morphology alterations, HJURP knockdown seems to induce cell death in both tumoral cells." (PMID 23638004, 2013). "HJURP mRNA was detected in extremely high levels in the majority of these tumors when compared with non-tumor white matter." (PMID 23638004, 2013). "HJURP is involved in the recruitment and assembly of the centromere and kinetochore, which are essential for accurate chromosome segregation, thereby playing a key role in maintaining chromosomal stability in tumor cells." (PMID 40299539, 2025). "Importantly, the co-culture of tumor cells with CAF-conditioned media results in an elevated HJURP expression and increased IC50 values, highlighting the functional relevance of this stromal–tumor metabolic axis." (PMID 40940809, 2025).
tumor (continued). "Firstly, we extracted tumor samples from a specific dataset and divided them into two groups based on a cutoff value of 0.3: the top 30% of samples with the highest HJURP expression and the bottom 30% with the lowest HJURP expression." (PMID 40290723, 2025). "Notably, several members of the panel, PLK1, UHRF1, and HJURP, have known roles in mitotic regulation and chromatin remodelling, both of which intersect with ferroptotic sensitivity and tumour aggressiveness." (PMID 41007424, 2025). "Additionally, we found that HJURP expression levels positively correlate with tumor cell density and negatively correlate with plasma cells, macrophages, endothelial cells, and fibroblasts." (PMID 39649097, 2024). "This indicates that HJURP is predominantly expressed in tumor cells." (PMID 39649097, 2024). "In addition, with the data of spatial transcriptomics and single-cell sequencing, we provide the new insight of the location of HJURP, that it’s most expressed in the tumor malignant cells, but less in immunocytes." (PMID 39649097, 2024). "In summary, HJURP may promote tumor progression in LUAD by influencing pathways related to the cell cycle and DNA damage repair." (PMID 39649097, 2024). "Similarly, both tumor-promoting and tumor-suppressing properties are attributed to HJURP overexpression, depending on the type of tissue." (PMID 39200236, 2024). "Additionally, we observed that patients with progressive disease in the TCGA-LUAD cohort had the highest HJURP expression in their tumor tissues (p = 0.036)." (PMID 39649097, 2024). "Finally, two studies that also retrieved data from TCGA database and incorporated 955 ccRCC tumor specimens in total attributed tumorigenic properties to HJURP overexpression." (PMID 37958340, 2023). "HJURP is involved in the recruitment and assembly of centromere and kinetochore and plays a key role in stabilizing the chromosome structure of tumor cells, and its dysfunction may contribute to tumorigenesis." (PMID 37025176, 2023). "In addition, functional experimental studies showed that HJURP acts as a tumor driver, promoting proliferation, migration, invasion, and epithelial-mesenchymal transition (EMT) and inhibiting apoptosis in HCC cells." (PMID 37025176, 2023). "Although HJURP has arisen as a potential biomarker for BC and a promising predictive indicator of sensitivity to tumor radiotherapy, further evaluation and validation of HJURP as a predictive marker for the diagnosis and prognosis of multimodal treatment of BC is clearly needed." (PMID 37025176, 2023). "Thus, the study highlights the potential role of HJURP as a tumor-promoting factor and a marker of worse prognosis in CCAs." (PMID 37958340, 2023). "In summary, HJURP has significant oncogenic effects in multiple tumor types." (PMID 37025176, 2023). "HJURP seems to play an overall tumor-promoting role in brain carcinogenesis." (PMID 37958340, 2023). "On the other hand, HJURP activates EMT through upregulation of Sphingosine kinase 1 (SPHK1), causing upregulation of vimentin and N-cadherin and downregulation of E-cadherin to promote tumor cell migration, invasion, and metastasis in vivo." (PMID 37025176, 2023). "The HJURP gene plays a role in promoting cell proliferation, which is closely related to tumorigenesis and may be involved in tumor development." (PMID 37025176, 2023). "Similarly, HJURP exhibits tumor-promoting properties in brain tumorigenesis, with its expression linked to patients’ poorer OS." (PMID 37958340, 2023). "However, in many tumors, contradictory data have been reported regarding the properties of DAXX and HJURP in neoplasia." (PMID 37958340, 2023). "Previous studies have shown that HJURP hypomethylation is associated with tumorigenicity, and the results showed that the HJURP gene was significantly hypomethylated in BLCA, KIRP, LIHC, PRAD and TGCT between tumor samples and normal samples." (PMID 36460821, 2022). "In CCA, HJURP was also highly expressed than para-tumor tissues." (PMID 35965590, 2022).
tumor (continued). "Then, the expression of HJURP was further evaluated using our own tumor specimens and cell lines." (PMID 35173547, 2022). "It has been reported that HJURP played an important role in human neoplasms." (PMID 35274047, 2022). "The immunohistochemical images showed HJURP/YAP1/NDRG1 axis promotes TNBC tumor growth." (PMID 35459269, 2022). "Finally, the composition pattern and immune infiltration of HJURP in different tumors were detected in Tumor Immune Estimation Resource." (PMID 36460821, 2022). "Similarly, ectopic expression of HJURP can promote proliferation, migration, and invasion of other tumor cells." (PMID 34434213, 2021). "HJURP was more highly expressed in 74.54% of tumor tissues than in normal tissues." (PMID 30111352, 2018). "HJURP expression was higher in HCC tissues than in para-tumor tissues." (PMID 30111352, 2018). "HJURP has been demonstrated to play an important role in human neoplasms." (PMID 30111352, 2018). "To test this hypothesis, we established a system allowing us to induce HJURP depletion in a tumor of measurable size." (PMID 28356341, 2017). "Our initial analysis added to the evidence that this tumor suppressor could play a role in the regulation of HJURP and CENP-A." (PMID 28356341, 2017). "A breakdown analysis as a function of lesion grade showed a significantly higher expression of HJURP in stroma (P = 0.031) and an expression of borderline significance (P = 0.063) in tumor cells in patients with relapsed G1-2 lesions compared to disease-free cases." (PMID 25243117, 2014). "Therefore, we suggest the upregulation of genes in our model work together in regulating cell cycle and tumor progression, with HJURP ensuring chromosome stability, CDK1 driving mitotic entry, and FOXM1 promoting proliferation and CHEK1 supporting cell survival under DNA damage conditions." (PMID 40299539, 2025). "In the GSE68465 cohort, age (p = 0.004), tumor grade (well vs moderate differentiation, p = 0.029), tumor T stage (T3 vs T1: p = 0.003, T4 vs T1: p = 0.004), tumor N stage (N1 vs N0: p < 0.001, N2 vs N0: p < 0.001), and HJURP expression (p < 0.001) were independent prognostic factors." (PMID 39649097, 2024). "Interestingly, HJURP also seems to act as a tumor suppressor in this specific organ." (PMID 37958340, 2023). "Similarly, HJURP appears to play a tumor-promoting role in SSs." (PMID 37958340, 2023). "Also, the relationship between HJURP and tumor immune infiltration was explored." (PMID 36460821, 2022). "The immune checkpoint molecule CTLA-4 demonstrated significant positive correlations with HJURP, VGF and COMP expression (p < 0.05), suggesting potential coordinated regulation of immune evasion and tumor progression pathways." (PMID 40592939, 2025). "HJURP enhances the viability, spheroid formation, migration, and invasion of PDAC cells in vitro, and it also promotes tumor growth and metastasis in vivo." (PMID 39093763, 2024). "Correlation analysis revealed a significant correlation of AURKA, AURKB, BUB1, HJURP, TOP2A, and TTK with tumor proliferation, G2M checkpoint, MYC targets, and DNA replication." (PMID 38726001, 2024). "In the GSE72094 cohort, gender (p = 0.003), tumor stage (Stage II vs Stage I: p = 0.004, Stage III vs Stage I: p < 0.001, Stage IV vs Stage I: p = 0.013), and HJURP expression (p < 0.001) were independent prognostic factors." (PMID 39649097, 2024). "Moreover, HJURP levels of expression were correlated with infiltration of various immune cells and expression of a wide range of immunocyte gene markers, showing that HJURP plays an essential role in the tumor microenvironment by regulating immunocyte infiltration." (PMID 37958340, 2023).
tumor (continued). "It is evident that HJURP enhances liver neoplastic process and can potentially aid in disease TNM staging, tumor grading as well as serve as a prognostic marker for patients’ DFS and OS." (PMID 37958340, 2023). "To conclude, DAXX has been reported as exerting both tumor-promoting and tumor-suppressing properties in CRC, while HJURP appears to play a protective role and was correlated with longer OS." (PMID 37958340, 2023). "HJURP significantly promoted the viability, sphere formation, migration, and invasion of PDAC cells in vitro, HJURP also facilitated tumor growth and metastasis in vivo." (PMID 32439850, 2020). "HJURP significantly promoted the viability, sphere formation, migration, and invasion of PDAC cells in vitro, and facilitated tumor growth and metastasis in vivo." (PMID 32439850, 2020). "Protein levels of HJURP in normal tissue (staining: Low; intensity: moderate; quantity: < 25%; Location: Cytoplasmic/membranou) (B) Protein levels of HMMR in tumor tissue (staining: Low; intensity: moderate; quantity: < 25%)." (PMID 31139013, 2019). "RT-qPCR and immunohistochemistry were used to detect HJURP expression in HCC and adjacent tumor tissues and HCC cell lines." (PMID 30111352, 2018). "A literature study reports data on tumor and stromal TG2 expression in 44 patients with in situ breast lesions in combination with HJURP and HIF." (PMID 27600076, 2016). "Protein expression of HJURP by immunohistochemical staining in 20 HCC tissues and paired adjacent non-tumor tissues." (PMID 26863619, 2016). "In our case series, the prognostic relevance of single markers was only observed for tumor and stromal expression of HIF-1α in the G3 subgroupand for stromal HJURP expression in G1-2 lesions." (PMID 25243117, 2014). "Although TG2, HJURP, and HIF-1α have proven to be important predictors of radiosensitivity in a number of tumor types, their role in the evolution of CIS has yet to be investigated." (PMID 25243117, 2014). "In tumour samples, immunoreactivity was observed in the nucleus for p60/CAF-1 and HJURP, and in the cytoplasm for PDLI4 and EDN/RB." (PMID 24039914, 2013). "Notably, when PCA was repeated using only the six prognostic genes (AQP4, CDCA3, HJURP, KIF20A, PLK1, UHRF1), tumour and normal samples remained partially separable." (PMID 41007424, 2025). "Conversely, the upregulated gene subset (e.g., SIM2, HJURP, IQGAP3, KIF18B) showed predominantly negative correlations with many IRGs, potentially reflecting an association with the suppression of anti-tumor immune responses." (PMID 41439026, 2025). "Our results revealed a significantly higher expression of HJURP in tumor tissues compared to their corresponding non-tumor tissues." (PMID 40290723, 2025). "Moreover, nuclear HJURP positivity was correlated with advanced T-status (Fischer’s exact test, p= 0.054, I versus II/III/IV, 44,4% versus 17.2%) and increased tumor size (Mann–Whitney U test, p = 0.030)." (PMID 39200236, 2024). "Mechanistically, knockdown of HJURP in NSCLC cells decreased the expression of β-catenin, cyclin D1, and c-myc, suggesting that HJURP may promote tumor progression by stimulating the Wnt/β-catenin pathway." (PMID 37025176, 2023). "In the TCGA-UCEC dataset, APOBEC3G, CUL4B, SCML2, TSPYL5, and ZBTB16 were significantly downregulated in tumor samples, whereas FOXP3, HJURP, HMGB3, and RAC3 were significantly upregulated in tumor samples, which was generally consistent with the result observed in GSE17025." (PMID 36936912, 2023). "For other types of neoplasms, such as those of the hematopoietic system, a limited number of studies support the protumorigenic role of DAXX and HJURP, rendering further investigations necessary to establish their function and possible application in the clinical setting." (PMID 37958340, 2023).